DPT (dermatopontin)
Description:
Seems to mediate adhesion by cell surface integrin binding. May serve as a communication link between the dermal fibroblast cell surface and its extracellular matrix environment. Enhances TGFB1 activity. Inhibits cell proliferation. Accelerates collagen fibril formation, and stabilizes collagen fibrils against low-temperature dissociation (By similarity).
Synonyms: TRAMP
Tractability: Antibody: UniProt places it where antibodies can reach, with medium confidence; UniProt predicts a signal peptide or a membrane-spanning region; its Gene Ontology location is reachable by antibodies, with medium confidence.
Gene: Protein-coding gene on chromosome 1 (168,695,457 to 168,729,206, reverse strand). Ensembl gene ENSG00000143196.
Subcellular location: Secreted, extracellular space, extracellular matrix
Subcellular location (Human Protein Atlas): Vesicles; Predicted to be secreted
Gene Ontology:
Molecular function: protein binding; extracellular matrix structural constituent
Biological process: collagen fibril organization
Cellular component: extracellular matrix; extracellular region; non-collagenous component of interstitial matrix
Genetic constraint (gnomAD): Loss-of-function variants: 21 observed, 31.39 expected, observed/expected ratio (o/e) 0.67, 90% interval 0.47 to 0.96. The upper end of that interval is the gene's LOEUF score, 0.96, which puts it in group 4 of 6, group 1 being the genes least tolerant of losing a copy. Missense variants: 260 observed, 270.44 expected, observed/expected ratio (o/e) 0.96, 90% interval 0.87 to 1.07. Synonymous variants: 90 observed, 91.52 expected, observed/expected ratio (o/e) 0.98, 90% interval 0.83 to 1.17.
Homologues: Orthologues: chimpanzee DPT (100% identical), macaque DPT (99% identical), dog DPT (96% identical), pig DPT (96% identical), rabbit DPT (95% identical), guinea pig DPT (94% identical), rat Dpt (93% identical), mouse Dpt (92% identical), tropical clawed frog dpt (74% identical), zebrafish dpt (55% identical).
Diseases named in the same sentence as DPT in open-access papers:
DPT is named in the same sentence as 62 diseases in open-access papers, as found by Europe PMC text mining. Sharing a sentence is not in itself a finding about the gene and the disease. The quoted sentences say what the papers report.
Obesity (6 papers, 2020 to 2025). Accumulation of substantial excess body fat. "Since visceral AT (VAT) exhibits a fundamental role in obesity-associated inflammation and colon carcinogenesis, the gene expression of DPT in this AT depot was also studied." (PMID 36012487, 2022). "We observed a stimulatory effect of LPS on the expression of DPT, suggesting the possible role of DPT in the inflammatory pathways associated to obesity." (PMID 32283761, 2020). "Further studies in larger cohorts to improve our insight of the role of DPT in obesity-associated breast cancer are needed and more studies on the dissection of signaling mechanisms of DPT-mediated angiogenesis might unravel novel targets for BC." (PMID 36774339, 2023). "Further studies in larger cohorts to improve our understanding of the role of DPT in obesity-associated CC are needed and more studies on the dissection of signalling mechanisms of DPT-mediated angiogenesis might unravel novel targets for tissue regeneration and cancer." (PMID 36012487, 2022). "Taken together, we proposed that DPT exerts an important role in the pathogenesis of ECM remodelling and inflammation during obesity and its associated comorbidities." (PMID 32283761, 2020). "We also report for the first time that DPT gene expression levels are increased in the VAT from patients with obesity as well as the role of DPT in the regulation of ECM remodelling and inflammation in human visceral adipocytes." (PMID 32283761, 2020). "A recent study identified six proteins (LEPR, IGFBP1, WFIKKN2, AGER, DPT, and CTSA), including WFIKKN2, which may have a causal role in the development of obesity." (PMID 39273278, 2024). "In contrast, the adipogenesis genes COL12A1, FBN1 and RBP4, as well as the genes CASP6 and DPT that involved in inflammation or immune response, were downregulated in obese pigs but upregulated in obese human, consistent with previous reports showing their upregulation in obesity." (PMID 40658709, 2025). "Thus, we aimed to examine whether obesity influences the serum levels of DPT and its mRNA levels in patients with CC." (PMID 36012487, 2022). "Given that the liver represents a main metabolic organ and that one of the best-recognized hepatic disorders related with obesity is NAFLD, our aim was to investigate the hepatic regulation of DPT and TGFB1 in this condition." (PMID 32283761, 2020). "In this sense, the study was designed to ascertain the role of DPT, a small protein with significant properties in collagen fibril formation, in regulating ECM remodelling and inflammation in VAT in the context of obesity." (PMID 32283761, 2020). "Based on these data, we presume that DPT influences ECM remodelling in HT-29 cells by modulating the expression of certain types of collagens and molecules that are dysregulated in inflammation, obesity or cancer." (PMID 36012487, 2022). "Although compelling evidence suggests that DPT regulates collagen fibrillogenesis, the role of DPT in regulating ECM remodelling and inflammation in VAT in a context of obesity remains unknown." (PMID 32283761, 2020). "CNTNAP2, GLI2, DPT (dermatopontin), AEBP1, ITIH5, CXCL11, GDNF (glial cell derived neurotrophic factor), MCHR1, FLT3, ELANE (elastase, neutrophil expressed), OSMR (oncostatin M receptor) and IL15RA are involved in development of obesity, but these genes might be key for progression of HF." (PMID 34218797, 2021).
oral squamous cell carcinoma (6 papers, 2012 to 2023). "Downregulation of DPT has been previously observed in oral squamous cell carcinoma and is associated with lymph node metastasis." (PMID 23236365, 2012). "In line with our findings, decreased expression of DPT has been demonstrated in oral squamous cell carcinoma, hepatocellular carcinoma and related cell lines, breast and ovarian cancers, as well as uterine leiomyomas." (PMID 34094025, 2021). "They showed that DPT expression in primary oral squamous cell carcinoma cells was significantly lower than in normal counterparts and correlated with regional lymph node metastasis." (PMID 25127546, 2014). "Down-regulation of DPT is also observed in oral squamous cell carcinoma (OSCC)-derived cells, which suggested that it might inhibit tumor invasion and metastasis." (PMID 25970782, 2015). "The authors postulated that downregulation of DPT is a characteristic event in oral squamous cell carcinoma and that this protein might play an important role in regulating tumor invasion and metastasis." (PMID 25127546, 2014). "Similarly, DPT expression level has a prominent decrease in human oral squamous cell carcinoma (OSCC)." (PMID 25149533, 2014).
breast carcinoma (5 papers, 2012 to 2025). "The genes are associated with laryngeal cancer (MEOX2), cervical cancer (FGF7), oral cancer (DPT), breast cancer (CILP) or ovarian cancer (TMEM119) and LAMP3-positive dendritic cells are generally associated with cancer." (PMID 38671536, 2024). "In brief, these in vitro and in vivo data showed that DPT serves as a vital anti-oncogene by inhibiting tumorigenesis in breast cancer." (PMID 36774339, 2023). "Here we found that DNMT3a-mediated DPT, promoter hypermethylation results in the downregulation of DPT expression in breast cancer and its low expression correlated with poor prognosis." (PMID 36774339, 2023). "We then performed rescue experiments to further confirm if YAP functions in DPT-mediated inhibition of breast cancer progression." (PMID 36774339, 2023). "To explore the expression of DPT in BC, we searched The Cancer Genome Atlas (TCGA) breast carcinoma database for differential expression between tumor tissues and normal mammary gland tissues." (PMID 36774339, 2023). "In leiomyoma, IPA shows a network connection between ERBB2 and DPT, a relationship previously undisclosed in studies of uterine leiomyoma or, to our knowledge, in studies of breast cancer." (PMID 23785396, 2013). "Recent studies have identified iCAF in several tumour types, including pancreatic cancer and breast cancer, using a variety of markers that encompass inflammatory cytokines and other genes (CXCL1, CXCL8, CXCL12, IL6, CFD, DPT)." (PMID 39757146, 2025). "In contrast to decreased TGFBI that has previously been associated with DCIS, decreased CADM3, DPT, and NID1 have not previously been linked to breast cancer." (PMID 23236365, 2012).
gastric cancer (5 papers, 2010 to 2024). A primary or metastatic malignant neoplasm involving the stomach. "Only three, CLDN7, CLDN1 and DPT, of these genes are significantly differentiated in all grades or stages of gastric cancer." (PMID 21445269, 2011). "DPT is significantly downregulated in gastric cancer tissues, and it may contribute to oral cancer metastasis." (PMID 34686626, 2021). "Among these genes, LRFN4, DPT, and LOC100506388 were identified as having a potential prognostic role in gastric cancer, as determined through a nomogram." (PMID 38609844, 2024). "FAM107A (Family With Sequence Similarity 107 Member A) with ADAM12, CEP55, LRFN4, INHBA, ADH1B, DPT, and LOC100506388 were analyzed and evaluated as potential prognostic genes for gastric cancer." (PMID 38609844, 2024). "LRFN4, DPT, and LOC100506388 were identified as potential prognostic genes for gastric cancer through a nomogram." (PMID 34686626, 2021). "Compared with normal tissues, ADAM12, CEP55, LRFN4, and INHBA were up-regulated in gastric cancer samples, while ADH1B, DPT, FAM107A, and LOC100506388 were downregulated." (PMID 34686626, 2021). "In the present work, comprehensive survival analysis and Cox regression analysis found that upregulation of DPT and LRFN4 correlated with good prognosis in gastric cancer patients." (PMID 34686626, 2021). "CDC2+DPT and CDC2+TOP2A are found to be good discriminators for five cancer types, namely breast, colon, lung, prostate and stomach cancers." (PMID 21060876, 2010).
hepatocellular carcinoma (5 papers, 2012 to 2022). A malignant tumor that arises from hepatocytes. "DPT has been reported to regulate cell proliferation and invasiveness of a variety of tumors like endometrial cancer, prostate cancer, hepatocellular carcinoma, and oral cancer." (PMID 36193505, 2022). "In a study on hepatocellular carcinoma and related cell lines, decreased expression of DPT mRNA and protein, despite increase in TGF-β protein (using IHC) was observed." (PMID 34094025, 2021). "Another study using quantitative real-time PCR showed that DPT was down-regulated in hepatocellular carcinoma and that the low expression level of DPT was correlated with more metastasis and worse survival." (PMID 34094025, 2021). "Reduced expression of DPT has been found in various neoplasms, including oral cancer, hepatocellular carcinoma, breast cancer, ovarian cancer, and leiomyoma." (PMID 34094025, 2021). "Li and colleagues showed that DPT is expressed in human liver and is significantly downregulated in hepatocellular carcinoma." (PMID 25127546, 2014). "Decreased expression of DPT in hepatocellular carcinoma has also been reported." (PMID 23236365, 2012). "In addition, DPT was shown to be down-regulated in hepatocellular carcinoma." (PMID 25149533, 2014).
colon cancer (4 papers, 2008 to 2022). "In this study, decreased expression of DPT was observed in 60.8% of colon cancers, and increased expression of DPT was seen in 21.5% of tumors." (PMID 34094025, 2021). "In this study, reduced expression of DPT was seen in 50% of proximal colon tumors, while only 33% of distal colon tumors showed a reduction in DPT expression." (PMID 34094025, 2021). "Matched Tumor/Normal expression Array 71.4% (5/7) of colon cancer samples showed down-regulation and 28.6 % (2/7) showed up-regulation of DPT in comparison with their normal counterparts." (PMID 34094025, 2021). "Regarding the tumor location, DPT underexpression was more common in proximal colon tumors than distal ones (50% vs. 32%), although the differences were not statistically significant." (PMID 34094025, 2021). "To study the possible effect that the molecules released by visceral adipocytes from patients with OB may have on colon cancer cells, we analysed the expression of DPT in HT-29 cells treated with the adipocyte conditioned medium (ACM)." (PMID 36012487, 2022). "Interestingly, we observed a strong (p < 0.01) increase in DPT mRNA levels in HT-29 cells treated with the ACM from volunteers with OB compared with the colon cancer cells incubated with the control media." (PMID 36012487, 2022). "Importantly, type I collagen reduces DPT mRNA levels, and DPT was down-regulated both in MG-thymoma and in colon cancer, suggesting inter-relationship between the observed changes." (PMID 18545673, 2008). "We found the best three single-gene discriminators for colon cancer are MMP7, DPT and MMP1 having 97.5%, 96.3% and 95.1% classification accuracy on the training set, and 97.9% and 90.9%, 97.9% and 74.6%, and 91.7% and 84.1% on the two test sets, respectively." (PMID 21060876, 2010).
oral cancer (4 papers, 2021 to 2024). "The low expression of DPT in oral cancer has also been validated by qRT-PCR, which substantiates the role of DPT as a common player in various cancers." (PMID 35625299, 2022).
systemic sclerosis (4 papers, 2011 to 2022). A chronic disorder, possibly autoimmune, marked by excessive production of collagen which results in hardening and thickening of body tissues. "DPT is a tyrosine-rich noncollagenous extracellular matrix component, and the depletion of DPT has been associated with hyperproliferation of scars, skin fibrosis, systemic sclerosis as well as some cancers." (PMID 36193505, 2022). "Down-regulation of DPT may be allied with uterine leiomyomas, systemic sclerosis, cutaneous fibrosis, and numerous cancers." (PMID 30970625, 2019). "The expression of DPT is down-regulated in cutaneous fibrosis, hypertrophic scarring, systemic sclerosis and uterine leiomyomas and keloids and may play an important role in wound healing." (PMID 25149533, 2014). "Dermatopontin and laminins have important roles in cell-matrix interactions and matrix assembly, and dermatopontin has been shown to be decreased in hypertrophic scar and systemic sclerosis skin fibroblasts." (PMID 22363853, 2011).
melanoma (3 papers, 2023 to 2024). A malignant, usually aggressive tumor composed of atypical, neoplastic melanocytes. "DPT is a candidate protein biomarker in tissue lysates of metastatic melanoma and is identified in tissue lysates of malignant melanoma by selected reaction monitoring." (PMID 38378847, 2024). "After literature research, we chose 6 hub genes: ALDH2, ADH1B, ALDH3A2, DPT, EPHX2, and GATM, which were rarely reported in melanoma as the object of this research to explore their accuracy in the diagnosis and prediction of melanoma." (PMID 38378847, 2024). "Taken together, ALDH2, ADH1B, ALDH3A2, DPT, EPHX2, and GATM are potential biomarkers of melanoma, which have high prediction values for melanoma." (PMID 38378847, 2024).
ovarian carcinoma (3 papers, 2015 to 2024). A malignant neoplasm originating from the surface ovarian epithelium. "Similarly, DPT also might be an ovarian cancer gene, as it is a cancer gene and is targeted by all ovarian cancer miRNAs." (PMID 25611546, 2015).
papillary thyroid cancer (3 papers, 2019 to 2021). "DPT is also involved in the inhibition of proliferation of keratinocytes, osteosarcoma cells, and papillary thyroid carcinoma cells in mice." (PMID 34686626, 2021). "Guo and coworkers additionally reported that DPT expression is downregulated in papillary thyroid cancer." (PMID 33033513, 2020).
keloid (2 papers, 2023). An irregularly shaped, elevated mark on the skin caused by deposits of excessive amounts of collagen during wound healing. "It has been reported that the keloid matrix lacks elastin fibers, hyaluronic acid, and dermatopontin, leading to stiffness in keloid tissues." (PMID 37587491, 2023).
leiomyoma (2 papers, 2008 to 2013). A well-circumscribed benign smooth muscle neoplasm characterized by the presence of spindle cells with cigar-shaped nuclei, interlacing fascicles, and a whorled pattern. "There was overlap in the identification of one gene in particular, DPT, which was significantly down-regulated in both the comparison between the two leiomyoma groups and in the comparison of all tumors to myometrium." (PMID 23785396, 2013).
pancreatic cancer (2 papers, 2022 to 2025). "Here in mouse models of pancreatic cancer, we provide in vivo genetic evidence that TGFβ receptor type 2 signalling in healthy dermatopontin+ universal fibroblasts is essential for the development of cancer-associated LRRC15+ myofibroblasts." (PMID 36171287, 2022).
prostate carcinoma (2 papers, 2020 to 2022). A carcinoma that arises from epithelial cells of the prostate gland. "We also identified multiple prostate cancer-associated genes such as cystatin C, PSCA, Cyp2e1, and dermatopontin that were remarkably underexpressed in CTRKO/LPB-Tag-CTRKO as compared to their WT and LPB-Tag counterparts, suggesting that CTR positively regulates these genes." (PMID 32180899, 2020).
prostate tumor (2 papers, 2020 to 2023). "SPP1 and CLDN8 were upregulated in prostate tumor tissues, whereas COL4A6, RND3, DPT, EFS, and TGFB1I1 were downregulated." (PMID 37251946, 2023). "Consistent with the microarray data, we found a higher expression of HMGCS1 (3.5-fold), HMGCR (2.5-fold), SCD1 (2.5-fold), AGPS (1.9-fold), FABP4 (2.5-fold), DPT (2.2- fold), and PTEN (1.56-fold decline) in prostate tumors of LPB-Tag genotype when compared with the prostates of other genotypes." (PMID 32180899, 2020).
thyroid cancer (2 papers, 2021 to 2024). "There is increasing evidence that DPT is involved in cell proliferation: it plays a role in wound repair and, when expressed at high levels, inhibits proliferation of thyroid cancer cells." (PMID 39775235, 2024). "DPT has been shown to inhibit cell proliferation through MYC repression and to be down-regulated in both oral and thyroid cancer." (PMID 34311724, 2021).
alcoholism (1 paper, 2020). "Spearman analysis of correlation between DPT and clinicopathological features revealed that the expression of DPT was significantly correlated with age (P = 0.049) and alcoholism (P = 0.029)." (PMID 33033513, 2020).
burn (1 paper, 2024). A traumatic injury involving interruption of tissue cohesiveness that results from exposure to caustic chemicals, extreme heat, extreme cold or excessive radiation. "In short, the effect of skin burn on patients is to regulate the expression of immune-related genes UPP1, MMP1, MMP3, and skin regeneration-related gene DPT, which may be the key target for the treatment of skin burn." (PMID 36103997, 2024).
childhood tumor (1 paper, 2016). "Considering the marked anti-tumor activity of the DpT analogues, their activity and mechanism of action was examined against the belligerent childhood tumor, neuroblastoma, in vitro and in vivo." (PMID 27678372, 2016).
colon adenocarcinoma (1 paper, 2021). "In the present study, the expression level of DPT in colon adenocarcinoma was analyzed using CPA arrays and real-time PCR, and aggregately in 60.8% (48/79) of the examined tumors the expression level was reduced." (PMID 34094025, 2021).
colorectal cancer (1 paper, 2021). A primary or metastatic malignant neoplasm that affects the colon or rectum. "This study aimed to investigate changes in DPT gene expression in colorectal cancer providing a better understanding of its carcinogenesis." (PMID 34094025, 2021). "The similarities between changing patterns of DPT and TGF-β expression in colorectal cancer demonstrate that DPT may act as a pre-receptor component of the TGF-β signaling pathway in colon carcinogenesis." (PMID 34094025, 2021).